SLC7A11 (solute carrier family 7 member 11)
Diseases named in the same sentence as SLC7A11 in open-access papers (continued):
Sharing a sentence is not in itself a finding about the gene and the disease.
cancer (continued). "SLC7A11 inhibition, cysteine deprivation, or targeting GPX4 have been reported to effectively enhance lipid peroxidation and induce ferroptosis in several cancer types." (PMID 40464376, 2025). "The regulation of some SLCs, such as SLC7A11, SLC1A5, and SLC38A9, are involved in cancer progression." (PMID 39949345, 2025). "Several key proteins interacting with ATF4 such as NRF2, GPX4, SLC7A11, PDIA4 have been suggested as mediators of the role ATF4 plays in preventing ferroptosis in various cancer models." (PMID 40667288, 2025). "SLC7A11‐mediated GSH synthesis plays a critical role in the antioxidant defence and survival of cancer cells." (PMID 39354653, 2025). "IR also induces an adaptive response involving SLC7A11 or GPX4 to inhibit IR-induced iron-dependent cell death and promote the survival of cancer cells during radiotherapy." (PMID 40219018, 2025). "The data presented here indicate that SLC7A11 is significantly upregulated in NSCLC tissues, and its knockdown impairs various cancer hallmarks, including proliferation, migration, invasion, tumorigenesis, and metastasis." (PMID 41030277, 2025). "In resistant TNBC, curcumol suppresses the SLC7A11/NF-κB/TGF-β pathway, but its derivative HCL-23 kills cancer cells death through HO-1-dependent ferroptosis." (PMID 41008615, 2025). "Through the production of IFN-γ and suppression of SLC7A11, activated CD8+ T lymphocytes would enhance LPO, especially in the ferroptosis of cancer cells." (PMID 40837737, 2025). "Co-transfection of METTL3 and SLC7A11 constructs showed that SLC7A11 overexpression attenuated METTL3-induced fluorescence intensity of C11-BODIPY and reduced sensitivity to erastin in METTL3-overexpressing cancer cells." (PMID 39800682, 2025). "NRF2 serves as a transcription factor that binds to the antioxidant response elements of SLC7A11 and GPX4 to suppress ferroptosis in cancer cells." (PMID 40223081, 2025). "Therefore, SLC7A11 may serve as a novel therapeutic target for cancer treatment." (PMID 41249582, 2025). "Moreover, 3′- UTR has been revealed to be effective RNA-based therapy tools for treating cardiac diseases irrespective of its cognate protein, the findings in this study suggested that mutated SLC7A11, GPX4 and CP 3′-UTRs may be effective RNA-based therapeutic targets for DOXIC in cancer patients." (PMID 40915108, 2025). "Recently, Hou, et.al conducted RNA sequencing of HepG2 cancer cells treated with Bevacizumab and found that Bevacizumab triggers cancer cells ferroptosis through the VEGF/PI3K/HAT1/SLC7A11 axis." (PMID 40670757, 2025). "have shown that selenium‐avid cancer cells employ SLC7A11 (a constituent of the cystine/glutamate antiporter SLC7A11) and xCT to facilitate increased selenium uptake, This, in turn, enables cancer cells to synthesize GPX4." (PMID 41323827, 2025). "Additionally, combining SLC7A11 inhibitors with other therapeutic agents, such as chemotherapy or immunotherapy, could result in synergistic effects, thereby enhancing treatment outcomes for patients with advanced-stage cancers." (PMID 40535572, 2025). "Therefore, for cancer cells that overexpress SLC7A11 and can evade ferroptosis, aside from inhibiting relevant pathways, we might shift the perspective from ferroptosis to disulfidptosis, as such cells are likely sensitive to nutritional deficiencies (such as glucose starvation)." (PMID 38739940, 2024).
cancer (continued). "Inhibition of miR-141-3p promoted Keap1 expression, inhibited Nrf2 and its downstream SLC7A11-GSH-GPX4 signaling pathway, as well as promoted ferroptosis in cancer cells, and inhibited paclitaxel and RSL3 resistance." (PMID 39308683, 2024). "In the current study, we thoroughly examined the mRNA levels of NCKAP1, SLC7A11, WASF2, RAC1, SLC3A2, and RPN1 as well as the relationships between the mRNA levels of these six genes in pan-cancer." (PMID 38968580, 2024). "Cytotoxic CD8+ T cells secrete interferonγ (IFNγ), which inhibits SLC7A11 by activating the JAK/STAT1 pathway in cancer cells, thereby inducing ferroptosis in cancer cells." (PMID 39238647, 2024). "Our data suggest that targeted inhibition of miR-141-3p promoted Keap1 expression and suppressed Nrf2 expression and inhibited SLC7A11-GSH-GPX4, the downstream anti-ferroptosis pathway of Nrf2, in cancer cells." (PMID 39308683, 2024). "Existing preclinical studies indicate that tumors with high SLC7A11 levels exhibit greater sensitivity to GLUT inhibitors, presenting a new direction for cancer therapy." (PMID 39687628, 2024). "This discovery has profound implications for the anticancer potential of niclosamide because SLC7A11 is considered as one of the promising drug targets for the treatment of not only TNBC, but also other cancers." (PMID 38539825, 2024). "In recent years, SLC7A11 has gained recognition for its crucial role in preventing ferroptosis by enhancing intracellular GSH levels, thereby positioning it as a cancer‐promoting oncogene." (PMID 39415848, 2024). "In summary, targeting different types of cancer through induction of ferroptosis is a promising therapeutic strategy, and several efforts are currently underway to develop selective GPX4, SLC7A11 and FSP1 inhibitors with enhanced bioavailability." (PMID 38908072, 2024). "Alternatively, the specific expression of SLC7A11 (SE = 1.5) in cancer stroma tumors is independently prognostic of poorer overall survival, and PDAC-derived CAFs are highly dependent on SLC7A11." (PMID 38892190, 2024). "Mechanistically, system Xc-, a cystine/glutamate antiporter system, composed of a light-chain subunit SLC7A11 (xCT) and a heavy-chain submit SLC3A2 (CD98), is a promising target for inhibiting ferroptosis in cancer cells." (PMID 38213727, 2024). "This was further reinforced by our prior study, which demonstrated that ICG in tandem with NIR encourages cancer cell ferroptosis through the down-regulation of GPX4 and SLC7A11." (PMID 38399278, 2024). "To investigate the role of four disulfidptosis-related genes (SLC7A11, SLC3A2, RPN1, and NCKAP1) in cancer progression, we divided TCGA patients into high and low expression groups based on the median expression levels of these four genes." (PMID 38166898, 2024). "Various agents capable of triggering ferroptosis predominantly target the SLC7A11-GSH-GPX4 pathway, leading to excessive lipid peroxidation in cancer cells." (PMID 39624080, 2024). "However, the precise regulatory mechanisms governing SLC7A11 expression and transporter activity and its specific role in controlling ferroptosis in cancer cells remain unknown, and these gaps in knowledge have attracted widespread attention in the scientific community." (PMID 39350768, 2024). "By upregulating the expression of SLC7A11 and SLC3A2, the cystine burden inside the cell increases, thereby promoting disulfidptosis in metabolically stressed cancer cells." (PMID 39590840, 2024). "Thus, low levels of KCTD10 coupled with high levels of USP18 would maintain elevated levels of SLC7A11 to enhance cystine uptake and subsequent metabolism, which could contribute to cystine addiction as often seen in cancer cells, which facilitates the spatial heterogeneity in cystine metabolism." (PMID 40440083, 2024). "This issue arises because ferroptosis inducers such as erastin and RSL3 target solute carrier family 7 member 11 (SLC7A11) and GPX4 - proteins expressed in both normal and cancer cells." (PMID 39534872, 2024).
cancer (continued). "Accordingly, genetic or pharmacologic inhibition of SLC7A11 leads to GSH depletion, GPX4 inhibition, and ferroptosis in many types of cancer." (PMID 39624080, 2024). "By inhibiting SLC7A11 or GPX4 with ferroptosis inducers (FINs), radioresistant cancer cells and xenograft tumors can be made more sensitive to IR." (PMID 39544291, 2024). "However, the precise role of SLC7A11 in the development of cancer remains unclear." (PMID 38862242, 2024). "The results revealed that SLC7A11, SLC3A2, RPN1, LRPPRC, and GYS1 were highly expressed in several cancer tissues." (PMID 38271056, 2024). "Since SLC7A11 is the upstream regulator of GPX4, we further elucidate the role of SLC7A11 in the anti-cancer effect of SFN against OS." (PMID 39657365, 2024). "SLC7A11, the cystine transporter protein, was identified as a critical BAP1 target gene in human cancers." (PMID 38267442, 2024). "Targeting SLC7A11, glucose transport or the PPP, inducing disulfidptosis, and killing cancer cells are potential treatment strategies." (PMID 38886311, 2024). "The levels of GPX4, SLC7A11, and SLC3A2 were reduced in cancer cells treated with either BRD4 knockout or JQ-1." (PMID 38565708, 2024). "Inhibition of SLC7A11 inhibits cysteine uptake and reduces GSH synthesis, and GSH depletion results in GPX4 inactivation, ROS accumulation, and ferroptosis in cancer cells." (PMID 38313306, 2024). "Specifically, targeting key antioxidant proteins, such as SLC7A11, GCLC, GPX4, TXN, and TXNRD, represents an emerging approach for inducing oxidative cell death in cancer cells." (PMID 39090114, 2024). "We found that the expression of GYS1 and SLC7A11 were upregulated, while those of NCKAP1, NDUFS1, NUBPL, OXSM, RPN1, and SLC3A2 were downregulated in ccRCC tissues compared with those in the para-carcinoma tissues." (PMID 38271056, 2024). "In xCT- and BECN1-overexpressing cancer cells, AMPK phosphorylates BECN1, induces binding to SLC7A11, and promotes ferroptosis by directly blocking xCT activity." (PMID 37842240, 2023). "In order to confirm the accuracy of the PCR array analysis and explore the role and correlation of CD44 and SLC7A11 in human CRC, population gene expression and survival analysis were performed using the pan-cancer data analysis tools GEPIA and ProGgene V2." (PMID 36672372, 2023). "It's previously reported that SLC1A5, SLC7A11, and GCLM are negative regulators that restrain ferroptosis in some kinds of cancers, while the remaining SAT1 facilitates ferroptosis." (PMID 35841206, 2023). "The SLC7A11 and GCLC are core regulators of ferroptosis and have been studied as promising targets in cancer." (PMID 37237981, 2023). "We assessed 19,221 genes and observed a positive correlation between FIN sensitivity and the expression of several well-known NRF2 targets, including NQO1, SLC7A11, GPX2, GCLC, and FTH1, across various cancer cell lines at both the mRNA and protein levels." (PMID 37633973, 2023). "Expression levels of the ferroptosis-related genes GCLC, MAP1LC3A, SLC7A11, and SLC39A8 in NAT10 KD cancer cells were significantly downregulated, therefore validating the results from our RNA-seq data." (PMID 37237981, 2023). "Thus, SLC7A11 expression could be a biomarker for the prognosis of cancers." (PMID 36874967, 2023). "Abnormal expression of SLC7A11, GPX4, and AIFM2 was found in a variety of tumors, which can be used to evaluate the prognosis and invasion degree of various cancers." (PMID 37894808, 2023). "Further immunohistochemistry showed that SLC7A11 and LRPPRC were higher in cancer tissues than in normal tissues." (PMID 37399661, 2023).
cancer (continued). "Our results showed significant downregulation in expression of essential genes related to ferroptosis, namely SLC7A11, GCLC, MAP1LC3A, and SLC39A8 in NAT10-depleted cancer cells." (PMID 37237981, 2023). "In contrast, SLC7A11 overexpression stimulates GSH production and suppresses ferroptosis in cancer cells." (PMID 37576601, 2023). "Antioxidant enzymes, such as TXNRD, glutathione reductase (GSR), and xCT/SLC7A11, are commonly up-regulated in cancer cells to counteract the unwanted oxidation derived from metabolism." (PMID 37836684, 2023). "SLC7A11 plays a crucial role in promoting the synthesis of GSH, which helps counteract oxidative stress and inhibits ferroptosis in various cancer cells." (PMID 37266741, 2023). "We show here that selenium/selenocysteine can be obtained by cancer cells via multiple routes: First by the SELENOP/LRP8 axis and second, via the activity of system Xc− (SLC7A11/SLC3A2)." (PMID 37435859, 2023). "COL12A1, ferroptosis markers and cancer stemness markers including GXP4, SLC7A11, Sox2 and Oct4 were obviously weakened by JYQHD." (PMID 37700383, 2023). "Intriguingly, OTUB1 is reported to stabilize SLC7A11 through CD44, which is known to be an important CSC marker in human cancers." (PMID 37726816, 2023). "The results of our systematic review and meta-analysis also indicated that high expression of SLC7A11 was statistically significant related to unfavorable OS, RFS, PFS and clinicopathological features in a number of human cancers." (PMID 36874967, 2023). "In contrast, overexpression of SLC7A11 promoted GSH biosynthesis and ferroptosis resistance in cancer cells." (PMID 37266741, 2023). "Next, we explored the potential involvement of rRNA production and ROS levels in the prognoses of both cancers by employing MPP10 and SLC7A11 as markers, respectively." (PMID 37087976, 2023). "Erastin is released to inhibit SLC7A11/SLC3A2, and Cu2+ further enhances cancer cell ferroptosis through the mutual conversion between Cu+ and Cu2+." (PMID 38288118, 2023). "Triggering ferroptosis in cancer cells has shown promising effects in cancer therapy by targeting key regulators such as GPX4 and SLC7A11, the key regulators of this form of cell death." (PMID 37558749, 2023). "During cancer immunostimulation, the secretion of TNF downregulates the expression of SLC7A11 and SLC3A2, and reduces the absorption of cysteine, leading to lipid peroxidation and iron deposition in cancer cells." (PMID 37681908, 2023). "Therefore, SLC7A11 could be a potential biomarker for human cancer prognosis." (PMID 36874967, 2023). "The expression of SLC7A11 is also upregulated by two oncogenic transcription factors, NRF2 and ATF4, thus suppressing ferroptosis and consequently enhancing cancer cell survival." (PMID 37087976, 2023). "The ferroptosis inhibitory gene solute carrier family 7 member 11 (SLC7A11) and glutathione peroxidase 4 (GPX4) inhibit ferroptosis in carcinoma cells." (PMID 37807410, 2023). "Nrf2 inhibits ferroptosis mainly by activating iron metabolism-related genes (SLC40A1 and MT1G), GSH metabolism-related genes (SLC7A11 and GCLM), and ROS detoxification enzymes (AKR1C1 and NQO1) in many cancers." (PMID 35847989, 2022). "For instance, previous study indicated that OTUB1 directly interacted with SLC7A11, which facilitated CD44-mediated effects on ferroptosis in human cancers." (PMID 35354355, 2022). "Erastin treatment or cystine deficiency induces SLC7A11 expression, but upregulating ATF3 suppresses SLC7A11 expression, depletes intracellular GSH, and promotes ferroptosis in cancer cells." (PMID 36552652, 2022). "The results showed that certain genes (such as GPX4, SLC7A11 and GSS) displayed higher expression, while others (such as ACSL1 and ACSL4) displayed lower expression in some cancer types." (PMID 34975326, 2022).
cancer (continued). "In other words, glucose deprivation disrupted SLC7A11-cystine-cysteine-GSH-mediated antioxidant system, which in turn boosted selenite-induced oxidative stress and cytotoxic effect against cancer." (PMID 35053507, 2022). "Cancer immunotherapy, such as anti-PDL1-mediated tumor immunotherapy, can downregulate SLC7A11 expression to trigger ferritin responses in cancer cells." (PMID 36686700, 2022). "The SLC7A11/xCT-GSH-GPX4 pathway, a classical regulatory pathway of ferroptosis, has been proven to be a powerful target for future treatment of various cancers, in which GSH plays an important role." (PMID 36033479, 2022). "CD44v-mediated upregulation of SLC7A11 promotes cystine supply and GSH synthesis, thereby inducing anticancer drug resistance in cancer cells." (PMID 36552652, 2022). "Thus, SLC7A11‐driven ferroptosis may represent a potential therapeutic target in cancer." (PMID 35522946, 2022). "xCT is coded by the SLC7A11 (solute carrier family 7, member 11) gene, and its overexpression is observed in various types of cancer cells, especially in cancer stem cells (CSC)." (PMID 36362074, 2022). "Therefore, SLC7A11 may be a potential therapeutic target in cancer by inducing ferroptosis." (PMID 36485069, 2022). "Inducing ferroptosis by either inhibition of the cystine/glutamate transporter, SLC7A11 (i.e., erastin) or glutathione peroxidase 4 (GPX4) (i.e., RSL3) has shown promising results in a variety of cancers." (PMID 36314903, 2022). "In cancer cells, BAP1 inactivation leads to the overexpression of SLC7A11, the suppression of ferroptosis, and the formation of tumors." (PMID 35408533, 2022). "Deubiquitinating H2Aub on the SLC7A11 gene promoter represses its expression, inhibiting cystine uptake and GSH synthesis and promoting ferroptosis in cancer cells." (PMID 36552652, 2022). "We extended these findings by using the a physiologically relevant concentration of KYN (45 μM of KYN) and four additional cancer cell lines, SKOV3, HT1080, PT45 and U2OS that showed varying baseline expression of SLC7A11." (PMID 35245456, 2022). "Consistent with our prior observations, and those of others, that eprenetapopt triggers GSH depletion in cancer cells, the CRISPRko screen identified genes involved in GSH synthesis, SLC7A11 and GCLM, while GCLC was the top enriched gene in the CRISPRa screen." (PMID 36103522, 2022). "In this study, we systematically analyzed the gene expression, epigenetic regulation, and genomic alterations of six key GLNM regulators (including SLC1A5, SLC7A5, SLC3A2, SLC7A11, GLS, and GLS2) across 33 different cancer types." (PMID 34573287, 2021). "In addition, one well-conducted study first proved CD8+ T cells could induce the ferroptosis in cancer cells via downregulating the SLC7A11 transcription and concomitant use of immune checkpoint inhibitors could synergistically enhance the anti-cancer capacity." (PMID 34938318, 2021). "Next, we analyzed the prognostic values of SLC7A11, GPX4, and AIFM2 in pan-cancer using GEPIA database." (PMID 34722530, 2021). "Through cancer genomic analyses, it was shown that SLC7A11 and BAP1 expression were inversely correlated in cancer." (PMID 33499222, 2021). "Overexpression of SLC7A11 was detected in KRAS-mutant lung adenocarcinoma (LUAD) and positively correlated with cancer progression." (PMID 34722530, 2021). "We further investigated the relationships between the expression levels of SLC7A11, GPX4, and AIFM2 and immune infiltration levels in pan-cancer by using the TIMER database." (PMID 34722530, 2021). "In previous studies, the glutamine transporters SLC1A5, SLC7A5, SLC7A11, and SLC3A2 were found to be highly expressed in a variety of cancers." (PMID 34573287, 2021).